ASAH1 (N-acylsphingosine amidohydrolase 1)
Description:
Lysosomal ceramidase that hydrolyzes sphingolipid ceramides into sphingosine and free fatty acids at acidic pH. Ceramides, sphingosine, and its phosphorylated form sphingosine-1-phosphate are bioactive lipids that mediate cellular signaling pathways regulating several biological processes including cell proliferation, apoptosis and differentiation. Has a higher catalytic efficiency towards C12-ceramides versus other ceramides. Also catalyzes the reverse reaction allowing the synthesis of ceramides from fatty acids and sphingosine. For the reverse synthetic reaction, the natural sphingosine D-erythro isomer is more efficiently utilized as a substrate compared to D-erythro-dihydrosphingosine and D-erythro-phytosphingosine, while the fatty acids with chain lengths of 12 or 14 carbons are the most efficiently used. Also has an N-acylethanolamine hydrolase activity. By regulating the levels of ceramides, sphingosine and sphingosine-1-phosphate in the epidermis, mediates the calcium-induced differentiation of epidermal keratinocytes. Also indirectly regulates tumor necrosis factor/TNF-induced apoptosis (By similarity). By regulating the intracellular balance between ceramides and sphingosine, in adrenocortical cells, probably also acts as a regulator of steroidogenesis. [Isoform 2]: May directly regulate steroidogenesis by binding the nuclear receptor NR5A1 and negatively regulating its transcriptional activity.
Synonyms: AC; ACDase; PHP32; ASAH; FLJ21558; PHP; SMAPME
Tractability: Small molecule: a structure with a bound ligand is known; a high-quality ligand is known. Antibody: UniProt places it where antibodies can reach, with high confidence; its Gene Ontology location is reachable by antibodies, with high confidence; UniProt predicts a signal peptide or a membrane-spanning region. PROTAC: ubiquitination databases record sites on it; its protein half-life has been measured; a small molecule that binds it is known.
Target class: Enzyme; Hydrolase
Gene: Protein-coding gene on chromosome 8 (18,055,992 to 18,084,998, reverse strand). Ensembl gene ENSG00000104763.
Subcellular location: Lysosome; Secreted; Nucleus (Isoform 2); Cytoplasm
Pathways (Reactome):
Developmental Biology: Regulation of MITF-M-dependent genes involved in lysosome biogenesis and autophagy
Immune System: Neutrophil degranulation
Metabolism: Glycosphingolipid catabolism
Gene Ontology:
Molecular function: hydrolase activity, acting on carbon-nitrogen (but not peptide) bonds, in linear amides; N-acylsphingosine amidohydrolase activity; protein binding; fatty acid amide hydrolase activity
Biological process: ceramide biosynthetic process; ceramide catabolic process; keratinocyte differentiation; regulation of steroid biosynthetic process; sphingolipid catabolic process; sphingomyelin catabolic process; sphingosine biosynthetic process; cellular response to tumor necrosis factor; regulation of programmed necrotic cell death; fatty acid metabolic process; sphingolipid metabolic process
Cellular component: early endosome; endoplasmic reticulum; extracellular exosome; extracellular region; lysosome; endolysosome lumen; ficolin-1-rich granule lumen; lysosomal lumen; tertiary granule lumen; cytoplasm; nucleus
Genetic constraint (gnomAD): Loss-of-function variants: 52 observed, 45.65 expected, observed/expected ratio (o/e) 1.14, 90% interval 0.91 to 1.43. The synonymous counts are far from expectation, so gnomAD's model fits this gene poorly and the ratio says little. Missense variants: 545 observed, 391.75 expected, observed/expected ratio (o/e) 1.39, 90% interval 1.3 to 1.49. Synonymous variants: 179 observed, 140.93 expected, observed/expected ratio (o/e) 1.27, 90% interval 1.12 to 1.44.
Gene-disease validity (ClinGen):
ClinGen rates the evidence that ASAH1 causes each of these diseases.
ASAH1-related sphingolipidosis (autosomal recessive): Definitive. A spectrum of disorders caused by variation(s) in the ASAH1 genel this spectrum includes Farber disease and spinal muscular atrophy with progressive myoclonic epilepsy.
Homologues: Orthologues: chimpanzee ASAH1 (94% identical), macaque ASAH1 (90% identical), dog ASAH1 (86% identical), rabbit ASAH1 (85% identical), rat Asah1 (83% identical), guinea pig ASAH1 (82% identical), mouse Asah1 (79% identical), pig ASAH1 (79% identical), tropical clawed frog asah1 (59% identical), zebrafish asah1b (59% identical), zebrafish asah1a (57% identical), Caenorhabditis elegans asah-1 (39% identical), and 1 more. Paralogues in human: NAAA (29% identical).
Diseases named in the same sentence as ASAH1 in open-access papers:
ASAH1 is named in the same sentence as 165 diseases in open-access papers, as found by Europe PMC text mining. Sharing a sentence is not in itself a finding about the gene and the disease. The quoted sentences say what the papers report.
Farber disease (49 papers, 2013 to 2025). "Farber disease is an autosomal recessive genetic disorder due to mutations in the gene responsible for acid ceramidase (ASAH1)." (PMID 38891023, 2024). "Acid ceramidase deficiency is an ultrarare autosomal recessive lysosomal storage disorder caused by pathogenic variants of the ASAH1." (PMID 37962265, 2023). "The SPTLC1- and SPTSSA-associated disorders represent the former case, while Farber Disease (deficiency of ceramidase encoded by ASAH1) corresponds to an example of the latter case." (PMID 36875645, 2023). "Farber disease is an LSD caused by a mutation in the ASAH1 gene encoding aCDase, leading to decreased enzymatic activity and Cer accumulation in the tissues." (PMID 38235387, 2023). "Farber disease is a rare autosomal recessive disorder, also known as Farber lipogranulomatosis, caused by a mutation in the ASAH1 gene, which leads to ceramide accumulation in several organs and tissues due to lysosomal acid ceramidase deficiency." (PMID 37601653, 2023). "Mutations in ASAH1 have been linked to two allegedly distinct disorders: Farber disease (FD) and spinal muscular atrophy with progressive myoclonic epilepsy (SMA-PME)." (PMID 37231125, 2023). "Mutations in the ASAH1 gene can result in Farber disease (FD) or spinal muscular atrophy with progressive myoclonic epilepsy (SMA-PME)." (PMID 36830643, 2023). "The deficiency of the gene for the aCerase synthesis, ASAH1, is responsible for two rare inherited disorders, Farber lipogranulomatosis (Farber disease) and spinal muscular atrophy with myoclonic epilepsy (SMA-PME)." (PMID 32098196, 2020). "Farber disease is caused by loss of function in acid ceramidase, ASAH1, resulting in the accumulation of ceramide, causing a multisystemic phenotype associated with early mortality." (PMID 32971894, 2020). "Mutations in the ASAH1 gene cause two different disorders, Farber disease (FD), a rare lysosomal storage disorder, and a rare form of spinal muscular atrophy combined with progressive myoclonic epilepsy (SMA-PME)." (PMID 32111095, 2020). "Farber disease is a lysosomal storage disorder characterised by loss-of-function mutations in acid ceramidase (ASAH1) that lead to ceramide accumulation, multiple-organ pathologies and early mortality." (PMID 31882772, 2019). "Acid ceramidase ASAH1 deficiency is the cause of Farber disease, while alkaline ceramidase (ACER3) variants are responsible for progressive leucodystrophy." (PMID 31284408, 2019). "They include ASAH1 (acid ceramidase, causing Farber disease), CLN10 (cathepsin-D, a lysosomal aspartyl proteinase causing neuronal ceroid lipofuscinosis), and SLC17A5 (sialin, causing Salla disease)." (PMID 31284408, 2019). "Farber disease (FD) is a rare autosomal recessive disease caused by mutations in the acid ceramidase gene (ASAH1)." (PMID 28733637, 2017). "Farber disease is inherited in an autosomal recessive fashion and is caused by mutations in the lysosomal acid ceramidase (ASAH1) gene." (PMID 23666771, 2013). "ASAH1 is also known as a gene for which mutated forms are responsible for Farber disease." (PMID 39457418, 2024). "Mutations in ASAH1 cause Farber disease and SMA with progressive myoclonic epilepsy (SMA-PME)." (PMID 37280710, 2023). "ACDase deficiency caused by mutations in ASAH1 leads to Farber disease (FD; OMIM#228000), also known as Farber’s lipogranulomatosis, an ultra-rare lysosomal storage disorder (LSD) in which ceramides and related sphingolipids such as sulfatide and GM3 ganglioside accumulate." (PMID 37231125, 2023). "Deficiency in ASAH1 induces ceramide accumulation, which is a major cause of Farber disease." (PMID 36113749, 2022). "Farber lipogranulomatosis (OMIM #228000) is caused by mutations in ASAH1 (Acid ceramidase), leads to the accumulation of lysosomal ceramide, causing neonatal joint deformities and a characteristic hoarse voice/cry, with life expectancy of approximately 2 years." (PMID 32351971, 2020).
Farber disease (continued). "Mutations in ASAH1 can result in acid ceramidase deficiency which may manifest as Farber Disease (FD, Farber Lipogranulomatosis, OMIM #22000), a rare inherited Lysosomal Storage Disorder (LSD)." (PMID 29379059, 2018). "For instance, in Farber disease, a fatal lysosomal storage disorder, mutations in the ASAH1 gene encoding acid ceramidase lead to ceramide accumulation." (PMID 40340648, 2025). "Farber disease is caused by mutations in the ASAH1 (in human)/Ash1 (in mouse) gene and the resultant deficiency of the ACDase, EC 3.5.1.23." (PMID 37189685, 2023). "Pathogenic mutations in the ASAH1 gene are responsible for spinal muscular atrophy with progressive myoclonic epilepsy (SMA-PME) and Farber disease, which overlapped with our patient's phenotype." (PMID 34377212, 2021). "Mutations in ASAH1 (acid ceramidase) and GALC (galactosylceramidase) lead to Farber lipogranulomatosis and Krabbe disease, respectively." (PMID 32435656, 2020). "Farber disease is caused by mutations in ASAH1 gene, which lead to decreased acid ceramidase activity and, in turn, to ceramide accumulation in almost every tissue of the body." (PMID 30669371, 2019). "Farber lipogranulomatosis, or Farber disease (FD), is an autosomal recessive LSD caused by a deficiency in acid ceramidase (ASAH1), the lysosomal enzyme that catalyzes the hydrolysis of ceramide." (PMID 29163032, 2017). "Genetic deficiencies in enzymes involved in sphingolipid metabolism, such as ASAH1 and SMPD1, are associated with lysosomal sphingolipid storage disorders such as Farber disease and Niemann-Pick disease, respectively, emphasizing the importance of maintaining proper sphingolipid balance." (PMID 41167398, 2025). "Farber disease (FD) and spinal muscular atrophy with progressive myoclonic epilepsy (SMA-PME) are ultra-rare, autosomal-recessive, acid ceramidase (ACDase) deficiency disorders caused by ASAH1 gene mutations." (PMID 36830643, 2023). "For Asah1 (Farber lipogranulomatosis) and Mcoln1 (mucolipidosis IV), where isogenic single and double mutants are both available, severe pathologies were associated only with the double mutant, suggesting that at least a portion of ohnologues share similar functions." (PMID 32435656, 2020). "Farber disease (FD) (OMIM 228000), also known as Farber’s lipogranulomatosis, is a rare autosomal recessive disease caused by mutations in the N-acylsphingosine amidohydrolase (ASAH1) gene (8p22)." (PMID 28733637, 2017). "Regarding the potential treatment strategies for Farber disease/SMA-PME, enzyme replacement therapy with recombinant acid ceramidase therapy and gene replacement therapy with ASAH1 cDNA are currently being investigated." (PMID 39457418, 2024).
melanoma (37 papers, 2011 to 2026). A malignant, usually aggressive tumor composed of atypical, neoplastic melanocytes. "The mRNA levels of ASAH1 (acid ceramidase, a ceramide-hydrolyzing enzyme), were higher in melanoma than in normal tissue, while SPHK1 mRNA (encoding sphingosine kinase 1) was not different between groups." (PMID 36077841, 2022). "In this study, we identified that ASAH1 is overexpressed in melanoma cells and its loss inhibits melanoma tumor growth and metastasis by suppressing peroxisome biogenesis and inhibiting peroxisome-associated ROS production." (PMID 33766731, 2021). "ASAH1 has been linked to several malignancies, including glioblastoma, acute myeloid leukemia, melanoma, prostate cancer, and colon cancer." (PMID 34102611, 2021). "To confirm the involvement of PPARγ in melanoma growth inhibition following ASAH1 loss, we simultaneously knocked down PPARγ and ASAH1 in melanoma cells." (PMID 33766731, 2021). "As described in further detail in the following sections, ASAH1 encodes the enzyme acid ceramidase (AC) that controls sphingolipid metabolism and modulates the phenotypic switch of melanoma cells." (PMID 31336922, 2019). "Since its products are involved in the regulation of cell proliferation, multiple studies have linked ASAH1 to multiple cancers such as melanoma, acute myeloid leukemia (AML), and colon and prostate cancers." (PMID 29899215, 2018). "Because its products are involved in the regulation of cell proliferation, multiple cancers have been linked to ASAH1, such as melanoma, acute myeloid leukemia (AML), and colon and prostate cancers." (PMID 29642535, 2018). "Here, we used the CrispR/Cas9 system to generate A375 melanoma cells in which AC is totally and stably depleted by a large deletion event in its encoding ASAH1 gene." (PMID 28785021, 2017). "Here we used CrispR-Cas9-mediated gene editing to delete the gene encoding for AC, ASAH1, in human A375 melanoma cells." (PMID 28785021, 2017). "ASAH1 is associated with tumor progression and invasiveness especially in melanoma, colon, and prostate cancers." (PMID 28445970, 2017). "The present study provides the first detailed description of the impact exerted by complete depletion of the ASAH1 gene, encoding for the lipid amidase AC, in a human melanoma cell line." (PMID 28785021, 2017). "Interestingly, a study in human melanoma cells showed lysosomal acid ceramidase controls the transition between invasive and proliferative phenotypes, with reduced ASAH1 expression associated with invasive behavior." (PMID 35562897, 2022). "Consequently, the melanoma cells developed an invasive property after the loss of ASAH1, thus losing their proliferative phenotype and acquiring enhanced motile properties." (PMID 35565311, 2022). "ASAH1 loss increased ceramide and peroxisome-derived ROS, which in turn inhibited melanoma growth." (PMID 33766731, 2021). "The auto anti-ASAH1 antibodies protected the melanoma patients from lymph node metastasis, and the loss of these antibodies could result in melanoma progression." (PMID 29899215, 2018). "Upregulation of an auto anti-ASAH1 antibody may mitigate melanoma metastasis; the loss of this antibody may result in melanoma progression." (PMID 29642535, 2018). "In addition, acid ceramidase (AC), encoded by the ASAH1 gene, which hydrolyses ceramide into sphingosine, is expressed at high levels in melanocytes and proliferative melanoma cells, as observed in vitro as well as in biopsies from patients with stage II melanoma." (PMID 32858889, 2020). "Furthermore, low ASAH1 expression was associated with invasive behavior of melanoma cells and therefore, may present a new therapeutic target." (PMID 32236130, 2020). "Among the ceramide metabolism genes being significantly downregulated in melanoma cell lines upon TNF treatment, we identified ASAH1, the gene encoding AC, the ultimate enzyme of sphingolipid lysosomal catabolism." (PMID 39136013, 2024).
melanoma (continued). "ASAH1 also promotes melanoma tumor growth and metastasis and its pharmacological inhibition enhances the effectiveness of BRAF kinase inhibitor." (PMID 38926346, 2024). "Silencing of ASAH1 suppresses melanoma growth, which can be attributed to the higher levels of intracellular ROS, stemming from increased peroxisome biogenesis (and therefore metabolism) as a result of PPARγ activation by accumulated ceramides." (PMID 38244103, 2024). "The deletion of ASAH1 in human A375 melanoma cells using CRISPR-Cas9-mediated gene editing showed a significantly greater accumulation of long-chain saturated Cers that are substrates for AC in ASAH1-null cells." (PMID 37760612, 2023). "In contrast to our findings, previous work in melanoma cells suggested that inhibiting ASAH1 increased pFAK." (PMID 35741006, 2022). "Though an ability of ASAH1 inhibition in blocking invasion of melanoma cells has been demonstrated, the effects on GBM cell migration of genetic targeting or pharmacologic inhibition of ASAH1 with carmofur have not been determined." (PMID 35741006, 2022). "Melanoma cells with high expression of ASAH1 display a proliferative state whereas low ASAH1 expression is associated with an invasive phenotype mediated by the activation of integrin/FAK signaling cascade." (PMID 35406721, 2022). "We showed that ROS regulation by ASAH1 through reducing peroxisome biogenesis facilitates melanoma growth, revealing an important role of peroxisomal biogenesis regulation in melanoma growth." (PMID 33766731, 2021). "To validate these results, we also analyzed ASAH1 protein expression in a melanoma tissue microarrays (TMAs) consisting of 121 samples of malignant melanoma and 56 normal skin controls using immunohistochemistry." (PMID 33766731, 2021). "ASAH1 knockdown in melanoma cell lines (A375, M14, MeWo, and YUGASP) increased PMP70 mRNA levels compared with cells expressing non-specific shRNA." (PMID 33766731, 2021). "ASAH1 expression was necessary to maintain melanoma tumor growth and metastatic attributes in cell cultures and mouse models of melanoma tumor growth and metastasis." (PMID 33766731, 2021). "We found that melanoma cells expressing ASAH1 shRNAs showed significantly higher firefly-luciferase reporter activity than cells expressing non-specific shRNA." (PMID 33766731, 2021). "The ASAH1 inhibitor was used alone or in combination with a BRAFV600E inhibitor to evaluate the therapeutic value of ASAH1 targeting for melanoma therapy." (PMID 33766731, 2021). "We determined that ASAH1 was overexpressed in a large percentage of melanoma cells and regulated by transcription factor E2F1 in a mitogen-activated protein (MAP) kinase pathway-dependent manner." (PMID 33766731, 2021). "Acid ceramidase (ASAH1) has been detected to be overexpressed in melanomas, conferring resistance to chemotherapy." (PMID 34357010, 2021). "To identify the transcription factors downstream of the MAPK pathway that regulate ASAH1 expression in melanoma cells, we analyzed the sequence of the ASAH1 promoter using the transcription factor/DNA-binding site prediction programs PROMO and rVISTA 2.0." (PMID 33766731, 2021). "Taken together, these data show that ASAH1 knockdown results in increased peroxisome biogenesis and peroxisome-derived ROS production, which suppresses melanoma growth." (PMID 33766731, 2021). "Collectively, these results show that the MAPK pathway increases E2F1 expression, which stimulates ASAH1 transcription in melanoma cells." (PMID 33766731, 2021). "We then compared the ability of ASAH1 N173Q mutant to rescue melanoma growth with that of wild-type ASAH1 using the soft-agar assay." (PMID 33766731, 2021). "We provide evidence that ASAH1 facilitates melanoma growth by suppressing peroxisome biogenesis and peroxisome-dependent ROS production." (PMID 33766731, 2021). "In previous work, we generated a human melanoma cell line in which the gene ASAH-1 was deleted using CRISPR-Cas9 editing." (PMID 33806766, 2021).